BRCA1 (BRCA1 DNA repair associated)
Diseases named in the same sentence as BRCA1 in open-access papers (continued):
Sharing a sentence is not in itself a finding about the gene and the disease.
serous carcinoma (continued). "Nevertheless, the studies that incorporate a systematic histopathologic review confirm and emphasize the greater frequency of high-grade serous carcinomas in BRCA1-associated tumors, with a frequency ranging from 67% to 100%." (PMID 25136623, 2014). "Earlier, by analyzing BRCA1 mutation, expression and promoter hypermethylation, we proposed a potential subclassification of high-grade serous adenocarcinomas into three groups: BRCA 1 loss through mutation, BRCA1 epigenetic loss and no BRCA loss." (PMID 20843305, 2010). "BRCA1 or BRCA2 abnormalities are present in most high grade serous carcinomas and lead to chromosomal instability through loss of the ability to repair double strand breaks by homologous recombination." (PMID 19798417, 2009). "Their results indicate that poorly differentiated serous carcinomas with BRCA1 mutations frequently show loss of PTEN." (PMID 18628764, 2008). "However, when tumor subtypes were analyzed, there was statistically significant increased risk of serous carcinomas in BRCA1 mutation carriers (observed to expected ratio of 22.2, 95%CI: [6.1,56.9], P < 0.001)." (PMID 38297203, 2024). "All of the detected BRCA1 P/LP variants were seen in patients with high-grade serous carcinoma." (PMID 34680387, 2021). "Also, in agreement with previous reports, we detected most BRCA1 mutations from serous carcinomas (7 out of 58 patients; 12.1%) and with lower frequency from endometrioid carcinomas (1 out of 14 patients; 7.1%)." (PMID 32856862, 2020). "The hallmark histopathologic diagnosis of HBOC-related tubo-ovarian cancer due to BRCA mutations is that of high-grade serous carcinoma, and the frequency of BRCA1 and BRCA2 germline mutations increases to approximately 25% in patients diagnosed with these neoplasms." (PMID 33117676, 2020). "Carriers of BRCA1/2 or any other tested gene pathogenic variants were more likely to be diagnosed younger, have first or second-degree relatives with OC, and have OC classified as high-grade serous carcinoma (HGSC)." (PMID 29348823, 2017). "All of the pathogenic BRCA1/2 mutations were identified in serous carcinoma samples (12/46; 26.1%)." (PMID 27907908, 2016). "However, the reported frequency of BRCA1/2 mutations in patients with high-grade serous carcinoma has been shown to vary between 19 and 30%, which is in line with the results of our study (26.1%)." (PMID 27907908, 2016). "Firstly, it is unclear whether high grade serous carcinomas with BRCA1/2 mutation differ in their miRNA expression patterns from non-mutation carrying cases; it is plausible that etiologically relevant differences in miRNA expression may be present." (PMID 19798417, 2009). "Significance analysis of microarrays (SAM) was performed to identify differences in miRNA expression between groups of high grade serous carcinomas with mutations in BRCA1, with mutations in BRCA2, with BRCA1 epigenetic loss and with no demonstrable BRCA1 or BRCA2 loss." (PMID 19798417, 2009). "The mechanism of BRCA1/2 loss is a potential method of subclassifying high grade serous carcinomas." (PMID 18208621, 2008). "It was possible to distinguish high grade serous carcinomas with BRCA1 mutations from those with epigenetic BRCA1 loss: tumours with BRCA1 mutations typically had decreased PTEN mRNA levels while those with epigenetic loss of BRCA1 had copy number gain of PIK3CA." (PMID 18208621, 2008). "However, only the association between BRCA1 gene hypermethylation and serous carcinoma was confirmed by multivariate analysis (P = 0.045)." (PMID 16928264, 2006).
serous carcinoma (continued). "However, inherited BRCA1/2 mutations are present in 13-15% of OC, most frequently (18% in high-grade serous carcinomas) and less commonly for other histologic subtypes and many cancer patients with BRCA1/2-wt tumors, sensitization to the different DNA-damaging agents with PARPi is less effective." (PMID 36910637, 2023). "Combining the TPVs detected through NGS and MLPA analyses (n = 74), most BRCA1/2 TPVs were detected in high-grade serous carcinoma (n = 67; 90.5%)." (PMID 38730634, 2024). "In serous carcinomas, genomic alterations of BRCA1 and BRCA2 accounted for 21.2% (166/784) and 14.7% (115/784) of cases, respectively." (PMID 38201563, 2023). "All germline BRCA1/2 large rearrangements were detected in tumour samples from patients diagnosed with advanced-stage, high-grade serous carcinoma, aged < 79 years (age range: 43 to 77 years old)." (PMID 38201604, 2023). "Using maintenance therapy with a PARP inhibitor provide more favorable progression-free survival among women with high-grade serous carcinoma (HGSC) and a BRCA1/2 mutation and homologous-recombination deficiency (HRD)." (PMID 36612230, 2022). "BRCA1 and BRCA2 mutation rates reported as 10% of serous carcinomas earlier, increased up to 40% in recent publications." (PMID 35147976, 2022). "In terms of genetic factors, the role of BRCA1 and BRCA2 mutations as risk factors for serous carcinomas has been established." (PMID 36233495, 2022). "BRCA1/2 alterations, PTEN loss, and gain of PIK3CA and CCND1 were characteristic for high-grade serous carcinomas." (PMID 33947352, 2021). "BRCA1 (3326A>T) and BRCA2 (1342A>C) mutations were co-existing in patients (II1, II3, and II5) identified as serous adenocarcinoma grade II." (PMID 32356124, 2020). "Among the 63 high-grade serous carcinomas, tumor stage and the expression of DBC1 were significantly associated with both OS and RFS, and the age of patients and BRCA1 expression were significantly associated with OS." (PMID 25823848, 2015). "CIMBA results confirm that over 70% of OCs in BRCA1 and BRCA2 mutation carriers are grade 3 serous carcinoma." (PMID 25136623, 2014). "Germline BRCA1 and BRCA2 mutations are predominantly associated with high-grade serous carcinoma formation." (PMID 23344037, 2013). "What is the mechanism underlying genomic instability and development of aneuploidy in ovarian high-grade serous carcinomas that lack BRCA1 and BRCA2 abnormalities?" (PMID 20843305, 2010). "In the current study, we examined the miRNA expression profiles of 328 human miRNAs in a series of ovarian serous tumors, molecularly characterized with respect to their BRCA1/2 status, focusing on high grade serous carcinomas." (PMID 19798417, 2009). "High grade serous carcinomas of different BRCA1/2 status exhibit highly similar miRNA expression patterns, with very few differences present." (PMID 19798417, 2009). "Little is known regarding the miRNA expression profiles of high grade serous carcinoma in relation to BRCA1/2 status, and compared to normal tubal epithelium, the putative tissue of origin for high grade serous carcinomas." (PMID 19798417, 2009). "In recent years, targeted therapies, particularly poly(ADP-ribose) polymerase (PARP) inhibitors, have emerged as effective treatments for high-grade serous carcinoma (HGSC) of the ovary, especially in tumors with defective homologous recombination repair or BRCA1/2 mutations." (PMID 40786960, 2025).
serous carcinoma (continued). "BRCA1/2 pathogenic variants were more frequently detected in patients diagnosed with high-grade serous carcinoma (54 versus 2 [non-high-grade serous carcinoma]) and those with advanced-stage disease (8 [FIGO stage I/II] versus 48 [FIGO stage III/IV])." (PMID 38201604, 2023). "Moreover, BRCA1/2 PV carriers were more likely to be in FIGO stage III-IV, andthe pathological type of BRCA1/2 PVs carriers wasmore likely to be high-grade serous carcinoma." (PMID 37546627, 2023). "According to the results found in the present study, in a population without a family history of cancer, the possibility of a BRCA1/2 somatic pathogenic variant in high grade serous carcinoma is 7%." (PMID 35986351, 2022). "Morphological features of BRCA1 and BRCA2 associated high-grade serous carcinoma." (PMID 33117676, 2020). "In high-grade serous carcinoma, we observed significant association with longer survival in women harboring BRCA1 or BRCA2 mutation as compared to patients without detectable mutation." (PMID 29587661, 2018). "High grade serous carcinoma patients with any loss within the BRCA1 gene show lower expression of miR-214 than patients with no change." (PMID 25705321, 2015). "More than half of high grade serous carcinomas overall possess some abnormality of BRCA1 or BRCA2." (PMID 19798417, 2009). "In the current study, miR-29a and miR-29b were found to be more highly upregulated in high grade serous carcinomas with any demonstrable BRCA1/2 loss compared to the group lacking demonstrable BRCA1/2 abnormalities by both microarray and qRT-PCR analyses." (PMID 19798417, 2009). "High grade serous carcinomas can be subclassified into three groups: BRCA1 loss (genetic), BRCA1 loss (epigenetic), and no BRCA1 loss." (PMID 18208621, 2008). "HRP high-grade serous carcinomas are molecularly heterogeneous; a lead candidate for negative predictive testing is the presence of high-level amplifications of CCNE1 given its mutual exclusivity to BRCA1/2 germline mutations as shown by Bowtell and colleagues." (PMID 35053578, 2022). "However, 10 no-high grade serous carcinoma and 49 cases with negative familiar history harbored BRCA1/2 pathogenic alterations." (PMID 35406410, 2022). "DNA ploidy and gene expression profile were used in order to compare gross genomic alteration and gene expression pattern between cases with BRCA1 loss through mutation, BRCA1 epigenetic loss, and no BRCA1 loss in cases of high-grade serous carcinoma with known BRCA1 and BRCA 2 status." (PMID 20843305, 2010). "It was also possible to subclassify high grade serous carcinomas into three groups: BRCA1 loss (genetic), BRCA1 loss (epigenetic), and no BRCA1 loss based on molecular alterations, which potentially may be used to guide treatment and determine prognosis." (PMID 24281034, 2010). "A total of 74 BRCA1/2 TPVs were detected in this cohort of Dutch EOC patients (14.7% of all tests), of which 90.5% were detected in high-grade serous carcinoma." (PMID 38730634, 2024). "The correlation coefficients of expression levels of BRCA1 and interaction partners in low-malignant-potential (LMP) and high-grade serous carcinoma (HGSOC) data sets." (PMID 27788148, 2016). "These include cells from high grade serous tumor (e.g., TOV2978G), high grade serous ascites (OV4453), adenocarcinomas (e.g. OVCAR3), serous adenocarcinomas (e.g., OVCAR4), low grade serous ascites (VOA1312_CL), other specific cell lines including snu8, and UWB1.289 (BRCA1 null)." (PMID 27129171, 2016).
serous carcinoma (continued). "Exome capture and DNA sequencing of 316 high-grade serous adenocarcinomas, however, did not identify any mutations in RAD51D, although 20% of tumours carried a germline or somatic mutation in BRCA1 or BRCA2." (PMID 22415235, 2012). "In this series of 28 high-grade serous carcinomas, gross genomic alteration characterized by aneuploidy did not correlate with BRCA1 status." (PMID 20843305, 2010). "What this does indicate, however, is that the same abnormality, chromosomal instability, appears to be present in all groups of high-grade serous carcinoma analyzed, irrespective of BRCA1 status." (PMID 20843305, 2010). "Overall, very few differences were observed in the comparisons between high grade serous carcinomas possessing mutation in BRCA1, mutation in BRCA2, epigenetic silencing of BRCA1, and no demonstrable loss in BRCA1." (PMID 19798417, 2009). "A few months later, a 55 years-old woman diagnosed with ovarian high-grade serous carcinoma tested negative for BRCA1/2 and PALB2 in a broad HBOC clinical panel (Ref.11 for the panel), however the same truncating variant c.1516G > T;p.E506* in MRE11A was identified." (PMID 33510186, 2021). "Although OCs of patients without a germline BRCA1 or BRCA2 mutation were selected based on their reported serous histology, revision revealed that 13% of these patients did not develop low‐ or high‐grade serous carcinomas (seven out of 54)." (PMID 27767231, 2017). "Therefore, the paucity of differences observed between these groups of serous carcinomas with different BRCA1 status is likely a reflection of intra-group non-uniformity and inter-group overlap in the gene expression patterns." (PMID 20843305, 2010). "Similarly, among high grade serous carcinomas, the expression of miR-29a and miR-29b were also significantly higher in group with BRCA1/2 abnormalities compared to group lacking demonstrable BRCA1/2 abnormalities." (PMID 19798417, 2009).
colon carcinoma (77 papers, 2002 to 2025). "Although there is still no consensus on the association between BRCA1/2 mutations and CRC, there is the suggestion that BRCA1 is associated with an increased risk of early-onset colon cancer but the association between CRC and BRCA2 mutation remains uncertain." (PMID 39156267, 2024). "BRCA1 is usually wild type in sporadic colon cancers, however, germline mutations to BRCA1 have been described to be increased in early onset colon cancers." (PMID 27197561, 2016). "Within the 3’ UTR of BRCA1, the homozygote variant genotype of rs8176318 was associated with increased risk of colon cancer (ORAA 1.34 95% CI 1.01, 1.78." (PMID 26630397, 2015). "In the family with the c.2805delAGAT mutation in BRCA1 (patient 39), one first-degree relative had breast and colon cancer." (PMID 22655046, 2012). "Increasing evidence shows that BRCA1 is widely associated with breast, ovarian and colon cancers." (PMID 33987081, 2021). "As colon cancer is rarely occurring in the families this might be a too strong recommendation, but our data suggest that it may be relevant for in example the BRCA1 ins6kbEx13 mutation." (PMID 30136106, 2019). "Some recent studies have indicated that miR-223-3p could down-regulate aNHEJ expression to result in synthetic lethality in human BRCA1-deficient cancers, and also act as an oncogenic miRNA in colon cancer through regulating EMT and PRDM1." (PMID 31661791, 2019). "Two of these SNPs were significantly associated with colon cancer, one being BRCA1 8176318." (PMID 29492227, 2018). "Although colon cancer cells usually express wild type BRCA1, presence of an oncogenic BARD1 splice variant (SV) in select cancers may render BRCA1 dysfunctional and allow cells to become sensitive to HR targeting therapies." (PMID 27197561, 2016). "Further research underscores the crucial role of ATF6 in DNA repair, which is achieved by maintaining BRCA-1 expression in colon cancer cells under ERS." (PMID 39080273, 2024). "In colon cancer cells, it conserves the expression of BRCA-1, thereby shielding the cells from cytotoxic effects mediated by ER stressors such as DPE and thapsigargin (TG)." (PMID 39080273, 2024). "Xeno-transplants of colon cancer EV-transformed BRCA1-KO fibroblasts displayed the epithelial colorectal cancer phenotype, indicating MET." (PMID 37371036, 2023). "Of note, colon cancer miRNAs, transferred through EVs to the BRCA1-KO fibroblasts, were also involved in the MET induction and subsequent acquisition of metastatic features." (PMID 37371036, 2023). "Of the 31 patients with early-onset colon cancer and advanced adenoma, 17 had germline testing, and 3 patients had PGVs (BRCA1, monoallelic EPCAM [OMIM 185535], and monoallelic MUTYH [OMIM 604933])." (PMID 37462969, 2023). "Of 31 patients with early-onset colon cancer found to have advanced adenomas, 17 had germline testing data, and 3 patients had PGVs (1 each in BRCA1, EPCAM [monoallelic], and MUTYH [monoallelic] genes)." (PMID 37462969, 2023). "This study shows for the first time that ATF6 sustains the expression level of BRCA-1 and protects colon cancer cells from the cytotoxic effect of ER stressors DPE and Thapsigargin." (PMID 35752616, 2022). "Colon cancer cell-derived EVs transfer various microRNAs to recipient BRCA1-knockout fibroblasts and induce a malignant phenotype." (PMID 32957712, 2020). "Following the observation that cancer EVs transfer RNA and DNA to target BRCA1-KO fibroblasts, we sought to further characterize the Evs-contained genetic components and confirm the transfer of colon cancer DNA to the BRCA1-KO fibroblasts." (PMID 31200749, 2019).